STAT3 (signal transducer and activator of transcription 3)
Diseases named in the same sentence as STAT3 in open-access papers (continued):
Sharing a sentence is not in itself a finding about the gene and the disease.
renal cell carcinoma (continued). "CircSAFB2 in renal cell carcinoma cell-derived EVs functioned as a miR-620 sponge while JAK1 and STAT3 protein levels were tested markedly lower after co-culturing with miR-620 mimics." (PMID 36405712, 2022). "This correlates with the result that renal cell carcinoma cell-derived EVs induce macrophages express a higher level of JAK1 and STAT3 protein, and miR-620 can prevent the JAK1 and STAT3 expression." (PMID 36405712, 2022). "G3BP1 contributes to the proliferation, migration and invasion of renal cell carcinoma (RCC), and knockdown of G3BP1 blocks the IL-6/STAT3 signaling and reduces the metastatic ability of RCC." (PMID 34526993, 2021). "A recent study supported the benefits of targeting Src-STAT3, which showed that Das and CYT387 (JAK/STAT inhibitor) together synergistically reduced proliferation and induced apoptosis of renal cell carcinoma." (PMID 32678032, 2020). "Among the different STATs, STAT3 and STAT5 are often constitutively active in various human cancers, including renal cell carcinoma (RCC), and control the expression of multiple genes involved in initiation, progression and chemoresistance." (PMID 26911335, 2016). "In patients with renal cell cancer (RCC), administration of a multikinase inhibitor Sunitinib capable of suppressing downstream STAT3 signaling resulted in decrease of MDSCs and Tregs along with increase of IFN-γ producing T cells." (PMID 23755373, 2013). "Furthermore, HRW suppressed vascular endothelial growth factor (VEGF) expression and signal transducer and activator of transcription 3 (STAT3) phosphorylation, thereby reducing the incidence of renal cell carcinoma and inhibiting tumor growth." (PMID 37893190, 2023). "In renal cell carcinoma, IL1R2 promotes tumor progression through the JAK2/STAT3 pathway." (PMID 37728418, 2023). "STAT3 is a transcription factor that enhances the progression of urothelial cells from carcinoma in situ to invasive bladder cancer and regulates the angiogenesis of RCC (renal cell carcinoma) through upregulating HIF1α and VEGF expression." (PMID 35123491, 2022). "The levels of G3BP1, which plays a critical role in stress granule (SG) formation, are increased in renal cell carcinoma (RCC) and promote IL6/STAT3 activation." (PMID 31952344, 2020). "Previous studies showed that leptin promoted viability and metastasis of renal cell carcinoma cells via activating the ERK1/2 and JAK/STAT3 signaling which could be partially abolished by ERK phosphorylation inhibitor U0126 and STAT3 phosphorylation inhibitor AG490, respectively." (PMID 27185268, 2016).
Arthritis (93 papers, 2012 to 2025). Inflammation of a joint. "Both NF-Kappa B and STAT3 signaling pathways are known to be linked to inflammation associated with cancer, dry-eye disease, arthritis, septic cardiomyopathy, and acute kidney injury." (PMID 40723823, 2025). "Facilitating role of skin inflammation for joint inflammation via crosstalk between keratinocytes and entheseal fibroblasts mediated by IL-6 and IL-23/Th17-associated STAT3 activation." (PMID 34485340, 2021). "When we crossed IL-1 cTg with either IL-6-, IL-17A/F-deficient or Stat3 conditional knockout mice, we observed significant inhibition of arthritis development." (PMID 30361689, 2018). "As a result, the mice overexpressing nuclear/cytoplasmic STAT3 had more severe arthritis (mean arthritis score: 11.6 ± 4.2) than did the control mice (mean arthritis score: 8.5 ± 2.0)." (PMID 39825104, 2025). "These targets modulate the IL-6/STAT1/STAT3 pathway, which has been shown to significantly prevent and treat gout and arthritis." (PMID 40170729, 2025). "Interactions between IL-18 and STAT3 have been shown in a spontaneous arthritis model, where the activation of STAT3 mediated IL-23-induced IL-17A production from CD4+ T cells." (PMID 40777291, 2025). "The observed amelioration of adjuvant-induced arthritis demonstratedmore robust control of the STAT3/p-STAT3 and JAK2/p-JAK2 pathways,indicating that these pathways hold significant promise as therapeuticstrategies for the management of RA." (PMID 39470172, 2024). "A collagen induced arthritis mouse model previously implicated JAK/STAT signaling in disease establishment and showed STAT3 was necessary for arthritis development." (PMID 39497832, 2024). "This is the first in vivo and in vitro evidence that SDSS exerts its role in ameliorating arthritis through suppressing the HIF-1α/STAT3/NLRP3 pathway, therefore modulating the inflammatory activation in macrophages." (PMID 36838542, 2023). "On the other hand, AMPK is involved in modulating the TH17-Treg imbalance via STAT3 inhibition in a collagen-antibody-induced arthritis model." (PMID 37174663, 2023). "Paeoniflorin can regulate signaling pathways (GPCR pathway, MAPKs/NF-κB pathway, PI3K/Akt/mTOR pathway, JAK2/STAT3 pathway, TGFβ/Smads, etc.)in experimental arthritis FLS." (PMID 37033930, 2023). "Considering these findings, we wonder if SDSS exerts anti-arthritis properties by inhibiting HIF-1α/STAT3/NLRP3 axis." (PMID 36838542, 2023). "The elevated expression and dysfunction of STAT3 lead to the persistence of synovial inflammation in RA patients and animal arthritis models." (PMID 35571141, 2022). "It has been shown that in IL-1 receptor antagonist knock mouse arthritis and CIA models, EGCG attenuates arthritis by inhibiting STAT3 and hypoxia induced factor-α which leads to reduction of Th17 cells." (PMID 35252279, 2022). "Local injection of liposomes with miR-17-5P mimic in arthritis mice joints can significantly alleviate inflammation and articular damage by directly targeting STAT3 and JAK/STAT pathways." (PMID 35350778, 2022). "STA21, a small molecule that inhibits the STAT3 pathway, was used to treat mesenchymal stem cells in the treatment of arthritis." (PMID 35090574, 2022). "In murine models, STAT1 activities often reduce arthritis severity, whereas STAT3 regulates leukocyte recruitment and activation, synovial hyperplasia and joint erosion." (PMID 34618359, 2022). "Abnormal activation of the JAK2/STAT3 pathway is closely involved in numerous inflammatory diseases progression, including arthritis, hepatitis, nephritis, and UC." (PMID 35220895, 2022). "Adiponectin enhances B-cell proliferation and differentiation via activation of Akt1/STAT3 and exacerbates collagen-induced arthritis." (PMID 35628866, 2022). "Classically, IL-6/gp130/STAT3 signaling has been viewed as a negative regulator of chondrocyte biology and function and is broadly discussed in the context of arthritis and other inflammatory diseases." (PMID 35039652, 2022).
Arthritis (continued). "It was also reported that the Ershiwuwei Lvxue pill (ELP) that is Tibetan traditional medicine, reduced collagen-induced arthritis through JAK2/STAT3-signaling pathway inhibition." (PMID 33917914, 2021). "In a study of mice with CIA, it was shown that inhibitor COX2, meloxicam, can inhibit STAT3 activation and act as an arthritis inhibitor blocking the formation of osteoclasts, thereby eradicating cartilage erosion." (PMID 33515210, 2021). "Recruitment of STAT3 or MAPK1/2 by OSM initiated remodeling in conditions like arthritis and osteoporosis and aided in the repair of fractures." (PMID 34221025, 2021). "Most inflammatory processes, including arthritis, implicate the STAT3 (signal transducer and activator of transcription) and NFκΒ (nuclear factor κΒ) pathways." (PMID 33530456, 2021). "This is an interesting observation regarding that STAT3-regulated SOCS3 expression in CD4+ T cells has been shown to be elevated in a cohort of 161 treatment-naïve early arthritis patients and in PBMCs from patients with active RA." (PMID 34630419, 2021). "The STAT3 pathway is involved in arthritis along with other cytokines and has been described earlier." (PMID 33515210, 2021). "In contrast, a dominant-negative STAT3 mutant with reduced STAT3 activity exhibits diminished cell infiltration into the joints, pannus formation, and cartilage damage in experimental arthritis in mice." (PMID 31694340, 2019). "Here, we show that activation of IL-1 signaling promotes major joint dominant arthritis, and that upregulation of either of IL-6, IL-17 or Stat3, which also function in RA, was required for arthritic phenotypes seen in hIL-1 cTg mice." (PMID 30361689, 2018). "Previous studies also revealed that IL23 was a central inflammatory cytokine in the pathogenesis of spontaneous arthritis in IL1Ra–/– mouse model likely by activating STAT3 signaling pathway." (PMID 30487798, 2018). "We then undertook a screen for reagents to inhibit Stat3 activation using ninety-six existing drugs, identified five candidate inhibitors, and found that three of those blocked arthritis in a CIA model." (PMID 28887478, 2017). "The STAT3 inhibitor STA-21 is another compound that interferes with STAT3 signaling leading to an improvement of the clinical course of arthritis in IL-1Ra–KO mice." (PMID 28098832, 2017). "Here, we provide evidence that signal transducer and activator of transcription 3 (Stat3) promotes inflammation and joint erosion in a mouse model of arthritis." (PMID 28887478, 2017). "A77 1726 treatment in arthritis mice exhibited attenuated expressions of STAT3 activity (both pSTATTyr705 and pSTAT3Ser727) in CD4+ T cells, whereas pSTAT5 activity in those cells was significantly augmented." (PMID 28193225, 2017). "In an arthritis model, it has been discovered that the Jak2/Stat3 pathway activates the transcription of antiapoptotic genes, such as Bcl2, and rescues chondrocytes from apoptosis." (PMID 27314053, 2016). "IL-17A, a major cytokine involved in arthritis, upregulates CXCL1, which is known to cause increased cell migration, angiogenesis, and activation of the STAT-3 pathway." (PMID 27102666, 2016). "The finding was consistent with a previous observation of the involvement of STAT3 signaling in patients with early arthritis." (PMID 25880754, 2015). "In the CIA model rats treated with VitA and VitE, the levels of p-STAT3 were significantly reduced, which is consistent with a previous study that showed p-STAT3 expression levels are upregulated in zymosan-induced arthritis." (PMID 25009608, 2014). "The result shows that inhibition of STAT3 reduced the arthritis score and the incidence of arthritis compared with that in mice treated with control." (PMID 25374443, 2014). "In line with the results in DIO mice, GSPE treatment in arthritis mice also exhibited attenuated expressions of STAT3 activity (both pSTAT3Tyr705 and pSTAT3Ser727) in CD4+ T cells, whereas pSTAT5 activity in those cells was profoundly augmented." (PMID 24223854, 2013).
Arthritis (continued). "Furthermore, the promotion of p-JAK2 and p-STAT3 was observed in the synovial tissues of MSU crystal-induced arthritis rats according to Yang's study." (PMID 36248423, 2022). "During the progression of arthritis, STAT3 induces the secretion of proinflammatory cytokines." (PMID 35090574, 2022). "In terms of STAT3, its phosphorylation by nuclear PKM2 has recently been implicated to mediate the pathogenic phenotype of coronary artery disease macrophages, inflammatory lung epithelial cells, EAE Th17 cells, and CD4+ T cells in a model of arthritis." (PMID 34858390, 2021). "Therefore, it seems appropriate to acknowledge the IL-6/STAT3/IL-17/NF-κB signaling cascade as a modulator of arthritis and potential therapeutic target." (PMID 33515210, 2021). "In addition to IL-6, IL-21 and IL-23 can induce STAT3, and both of these compounds take part in arthritis." (PMID 33515210, 2021). "In M1-polarizing conditions, 65–79*SE was predicted to stimulate activation of pro-inflammatory, pro-RA upstream regulators, such as Stat3, Rel, Rela, Jun, Ctnnb1 and Hif1a, among others, and to inhibit anti-arthritis or anti-inflammatory regulators (e.g. Klf2, Xbp1, Foxp3)." (PMID 33510427, 2021). "Stat3 is also reportedly required for arthritis development in RA37–39." (PMID 30361689, 2018). "Furthermore, the IL-17-triggered positive feedback loop between IL-17 and IL-6 and its downstream effector Stat3 reportedly promotes arthritis development in gp130 mutant F759 mice." (PMID 30361689, 2018). "However, joint inflammation, as assessed by an arthritis score, was significantly decreased in Stat3 cKO relative to control mice at the indicated time points." (PMID 28887478, 2017). "In this study, we demonstrated that Stat3 is a key regulator of both RA-related events and that inhibiting its activity is sufficient to block both inflammation and osteoclast activities in joints in a mouse model of arthritis." (PMID 28887478, 2017). "Activation of STAT3 has been described in monocytes from synovial fluid and in T cell infiltrate in the joints of patients with RA, and results from experimental arthritis models support the concept that STAT3 promotes arthritis when activated in the joints." (PMID 26353115, 2015). "We also investigated whether IL-32β inhibited inflammatory gene expression by the inhibition of NF-κB and STAT3 signals in the paw joint, and thus suppresses the development of arthritis." (PMID 26497686, 2015). "Furthermore, STAT3 inhibitor significantly suppressed IL-17 production and attenuated the arthritis score and the incidence of arthritis." (PMID 25374443, 2014). "Inducing the local activation of STAT3 in bone cells may be a valuable tool to increase bone formation in osteoporosis and arthritis, and in localised bone remodelling during fracture repair." (PMID 22802946, 2012). "Moreover, analysis of CD4+ T cells from inguinal draining lymph nodes of gp130Y757F:Y757F mice with arthritis showed that genetic ablation of Stat1 in these animals enhanced the expression of several STAT3 regulated cytokines involved in T cell‐driven synovitis." (PMID 34618359, 2022). "Curcumin attenuated the severity of arthritis and reduced synovial hyperplasia by modulating the inc00052/miR-126-5p/PIAS2 pathway through the JAK2/STAT3 signaling mechanism, thereby providing protective effects against RA." (PMID 39974740, 2025). "A recent study showed that DHA exhibited significant therapeutic effects on arthritis by reducing HIF-1α expression and the phosphorylation of JAK3 and STAT3." (PMID 40841966, 2025). "In collagen-induced arthritis and collagen antibody-induced arthritis mouse models, ferroptotic M2 macrophages released HMGB1, which engaged TLR4 and activated STAT3 signaling in M1 macrophages, fueling inflammatory amplification loops." (PMID 40722994, 2025). "Utilizing SF from patients with arthritis, we show that DC3s can develop from DC2s in response to IL-6 and JAK/STAT3 signaling." (PMID 40687784, 2025).
Arthritis (continued). "In an adjuvant-induced arthritis model of RA, CCR2, and the expression of other chemokines were increased, accompanied by increased activation of JAK/STAT1/STAT3 pathways, as well as macrophage and endothelial cell infiltration." (PMID 37457301, 2023). "A CIA mouse model was established and divided into control, model, and PNS (100 mg/kg) groups to assess an anti-arthritis effect, Th17 cell differentiation, and PKM2/STAT3 expression." (PMID 36794740, 2023). "Research confirms that IL-6 has a pivotal role for STAT3 activation in CD4+ T cells, especially for pathogenesis of ACPA-negative arthritis." (PMID 33515210, 2021). "Interestingly, it has been demonstrated that the WNT5A gene has a binding site for STAT3, and that its expression is regulated by this transcription factor, playing a very important role in the maintenance of a chronic inflammation state, as well as in the destruction of cartilage in arthritis." (PMID 29584756, 2018). "M10 ameliorated arthritis in the CAIA model, and inhibited RANKL, WNT5A, and Bcl-2 expression in RA FLS by blocking IL-6 signaling, likely via Janus kinase–STAT3 pathway downregulation." (PMID 29755657, 2018). "Previous studies showed that PFS suppressed Freund’s Complete Adjuvant induced rat arthritis (AIA) by downregulating mRNA levels of IL-6 and TGF-β1 in vivo and reducing joint protein expression levels of phospho-STAT3 and IKKα." (PMID 28463993, 2017). "In addition, rebamipide, a drug for treatment of UC, also attenuates the inflammation in arthritis and gut by rebalancing the Treg/Th17 cells, suppressing TNF-α, IL-17 level and modulating splenic STAT3 activity." (PMID 33967779, 2021). "LMT-28 could alleviate arthritis and acute pancreatitis in mice, reduce the secretion of TNF-α in serum, and inhibit IL-6-induced phosphorylation of Stat3, gp130 and JAK2 proteins." (PMID 34955842, 2021). "Ingenuity pathway analysis identified inflammatory pathways in arthritis along with classic cachexia pathways, including PI3K/Akt signaling, acute phase response signaling, STAT3 pathway, NF-kB signaling, coagulation and complement system, and IL-6 signaling pathways." (PMID 33334063, 2020). "Noteworthy is the complete remission of CNS inflammation (patient 2), arthritis (patient 3), and ILD (patient 3) as well as the improvement of trachyonychia (patient 4) under baricitinib, whose effectiveness for STAT3-GOF-associated immune dysregulation has not been reported previously." (PMID 39247195, 2024).